POSTN (periostin)
Diseases named in the same sentence as POSTN in open-access papers (continued):
Sharing a sentence is not in itself a finding about the gene and the disease.
cancer (continued). "POSTN has been shown to counteract hypoxia-induced apoptosis in cancer cells." (PMID 29946533, 2018). "We next investigated how periostin promotes the proliferative ability of cancer cells." (PMID 30131847, 2018). "The fact that POSTN can modulate the hallmarks of cancer suggests that this multifaceted protein can have implications for cancer diagnosis and prognosis and, more importantly, for the development of therapies targeting POSTN function." (PMID 29946533, 2018). "Periostin has been shown to promote EMT in several types of cancer cells." (PMID 29946533, 2018). "High periostin expression in cancer cells may be a novel parameter for the prediction of prognosis in patients with IBC." (PMID 29161296, 2017). "Periostin is a mesenchymal component, therefore, increased periostin expression in cancer cells may reflect the acquisition of EMT and is an early event in breast tumorigenesis." (PMID 29161296, 2017). "Periostin, a fasciclin-containing adhesive ECM glycoprotein, is frequently overexpressed in various types of human cancer, and its overexpression in cancer-associated stroma and/or cancer cells is usually associated with poor clinical outcomes." (PMID 29161296, 2017). "In addition, POSTN is known to activate the canonical wingless-related integration site (Wnt) signaling pathways, which are involved in cancer stem cell maintenance." (PMID 29065446, 2017). "In this context, periostin was shown to promote adhesion and migration of cancer cells, vascular smooth muscle cells, and mesenchymal stem cells or facilitate the infiltration of macrophages into the cancer tissue." (PMID 28536691, 2017). "Within the list of top differentially expressed genes, in the UCHL1 KDs we found downregulation of the Wnt targets POSTN, SP7, and DLL1, of the transporter ABCA4, of the homeobox gene DLX4, and of genes recently linked to cancer progression ACTA2, AQ4, GRAP2, and ALK." (PMID 28472177, 2017). "Our finding provides a novel insight into the role of periostin in cancer metastasis and indicates that periostin may potentially be a useful target for metastasis treatment." (PMID 28977942, 2017). "Elevated levels of POSTN have been detected in sera from patients with various types of cancers, suggesting that POSTN may be a useful biomarker for those cancers." (PMID 29065446, 2017). "Periostin is suggested to be required for cancer stem cell maintenance and metastasis." (PMID 28088789, 2017). "The EMT of cancer cells is characterized by a downregulation of epithelial markers such as E-cadherin, α-cadherin, and γ-cadherin and acquisition of a mesenchymal phenotype, accompanied by upregulation of periostin, vimentin, fibronectin and N-cadherin." (PMID 28977942, 2017). "Overexpression of periostin has also been observed in a number of other human cancers." (PMID 26981774, 2016). "Additionally, bioinformatics analysis revealed that an intact p73/POSTN axis, where POSTN and p73 expression is correlated, predicts bad prognosis in several cancer types." (PMID 26930720, 2016). "Myofibroblasts also secrete periostin that acts in several ways to promote cancer." (PMID 27515461, 2016). "Notably, we observed that POSTN was mainly expressed in the stromal cells of HNC tissues and adjacent normal tissues, and the expression of POSTN in the stroma of cancer tissues was much higher." (PMID 26857387, 2016). "Moreover, periostin is secreted from cancer cells and has the ability to promote their migration and enhance their invasiveness by interacting with integrins." (PMID 27589561, 2016). "In NSCLC, POSTN in cancer stroma cells is a prognostic factor for poor progression-free survival." (PMID 26716408, 2016). "Thus, stromal POSTN whose expression accumulates during CRC progression promotes cancer cell survival, growth, and invasiveness via activating oncogenic pathways such as PI3K/Akt and/or Wnt/β-catenin pathways." (PMID 26556874, 2016).
cancer (continued). "Protein expression of POSTN can be observed in the cancer stroma and cancer cells." (PMID 26716408, 2016). "Hence, we believed that it was the cancer stroma, especially CAFs, that functioned as the principal source of POSTN in HNC tissues." (PMID 26857387, 2016). "Based on our results and the published data, we hypothesize that POSTN derived from colonic fibroblasts facilitates the evolution of cancer stem cells via activating PI3K/Akt and/or Wnt/β-catenin signaling pathways." (PMID 26556874, 2016). "Because POSTN was expressed in CAFs from cancer tissues, but was weak in cancer cells, we hypothesized that the interplay between fibroblasts and cancer cells might contribute to the high expression of POSTN." (PMID 26857387, 2016). "These evidences indicate that stromal POSTN may be re-expressed by proinflammatory factors in chronic tumor-supportive inflammation, and facilitate cancer evolution and development via creating a cancer-supportive niche." (PMID 26556874, 2016). "In this regard and contrary to the enhanced migration induced in fibroblast by periostin, invasion and migration capacities of cancer cells may be also negatively affected by the presence of periostin." (PMID 26809067, 2016). "Very importantly, the secretory protein periostin that has been suggested to function as a cell adhesion molecule and promote the invasiveness or growth rate of tumors is highly expressed by PSCs compared to cancer cells in humans." (PMID 26029109, 2015). "As such we hypothesized that sasRNAs targeted to direct TGS of Periostin could inhibit invasive and metastatic potential of cancer cells." (PMID 26543579, 2015). "Similar to α-SMA expression, moderate/high expression of periostin was observed in the majority of cases (n = 166; periostin-positive), with periostin localised to the cancer cell–stromal interface, corresponding to areas of high α-SMA expression in keeping with a myofibroblastic CAFs origin." (PMID 25345775, 2015). "Altered expression of Periostin is reported in a number of different forms of cancer." (PMID 26543579, 2015). "Among the 10 paracrine factors were both known and unknown cancer promoting stromal factors, the former including Placental Growth Factor (PGF) and Periostin (POSTN), while Pregnancy-Associated Plasma Protein A (PAPPA) was among the latter." (PMID 26020769, 2015). "Periostin is usually localized to the periphery of stromal cells surrounding carcinoma cells." (PMID 25852822, 2015). "Periostin may bridge the gap between the metastatic microenvironment and cancer stem cells to promote metastatic spread by augmenting the Wnt signaling pathway." (PMID 24146092, 2014). "In the present study, periostin was upregulated in the NSCLC and chronic inflammation patients, therefore we hypothesize that periostin may be a member of the matricellular protein family and that it has an effect on chronic inflammation and cancer." (PMID 24273600, 2013). "Current knowledge about Periostin biology has expanded from its recognized functions in embryogenesis and bone metabolism to its roles in tissue repair and remodeling and its clinical implications in cancer." (PMID 24349533, 2013). "We considered that periostin may be pivotal in the pathogenesis and development of NSCLC, and that chronic inflammation may promote cancer development using certain molecules, including periostin." (PMID 24273600, 2013). "Periostin recruits Wnt ligands and thereby increases Wnt signaling in cancer stem cells." (PMID 24273600, 2013). "In recent studies, periostin was reported as a bridge between cancer stem cell and metastasis." (PMID 23056395, 2012). "Periostin mediates the crosstalk between cancer stem cells and their niche." (PMID 23056395, 2012). "However, all reports including the present study showed that increased level of periostin was observed in cancer patients." (PMID 22952986, 2012).
cancer (continued). "In addition to forming bones, teeth, and heart, periostin was recently found to be overexpressed in various types of human cancer." (PMID 22110952, 2011). "A comprehensive understanding of periostin's functional spectrum is still actively developing, but certain core aspects emerging from those three major areas (skeletal development, heart development and disease, and cancer) are coming increasingly into focus." (PMID 20109226, 2010). "Periostin expression was found in both epithelial cancer cells and in peritumoural stroma." (PMID 20534149, 2010). "Over the past seven years, periostin was proposed to be a novel therapeutic target for cancer." (PMID 18086302, 2007). "However, other studies reported a down-regulation of POSTN transcription in bladder and lung cancer." (PMID 18086302, 2007). "Notably, periostin has been shown to increase VEGF expression in cancer and other disease states." (PMID 40053143, 2025). "Fourth, although our in vitro experiments support the cell-autonomous effect of POSTN, the non-autonomous role of POSTN in LUAD recurrence (paracrine effects from cancer-associated fibroblasts) remains to be clarified through co-culture or conditioned medium assays." (PMID 40991535, 2025). "In addition, POSTN acts as a scaffold for many other proteins and is involved in signal transduction from cells to the matrix and epithelial-to-mesenchymal transition, thereby promoting cancer progression and the development of chemoresistance." (PMID 40991535, 2025). "Mechanistically, POSTN activates integrin–FAK/NF-κB signaling, inducing cytokines (MIP-1β, MCP-1, TNF-α, RANTES), thereby enhancing monocyte chemotaxis and M2 polarization; metastases from POSTN-overexpressing SKOV3 cells were enriched in cancer-associated fibroblasts (CAFs)." (PMID 40963633, 2025). "Indeed, Masson-Trichrome and picrosirius red staining showed high levels of collagens adjacent to the carcinomas and immunohistochemistry validated increased levels of Laminin β1, Laminin γ1, Fibronectin, Periostin and Tenascin C, most of which showed a discrete pattern adjacent to the carcinomas." (PMID 39953252, 2025). "Indeed, myMAF CM enhanced cancer cell colony formation in a periostin-dependent manner." (PMID 38678021, 2024). "Therefore, we could speculate that POSTN has anti-apoptosis effect on cancer cells, moreover, this effect is closely related to hypoxia." (PMID 37572219, 2023). "Periostin as a cell-secreted protein may be upregulated for a wide range of cancers leading to cell survival, epithelial to mesenchymal transition (EMT), and angiogenesis, and may play a pivotal role in matrix cell signaling as a cytokine molecule related to EMT cues." (PMID 36671668, 2023). "In contrast, periostin (POSTN), which is significantly upregulated in bulk RNA-seq but was not included in our integrated bulk-spatial transcriptomic analysis, was demonstrated by immunofluorescent staining to be a marker in fibrous tissues surrounding cancer clusters." (PMID 37370820, 2023). "Notably, the removal of Periostin from the serum halted the proliferation of cancer cells in vitro." (PMID 38139195, 2023). "Therefore, we focused on the role of novel cancer cell‐derived POSTN isoform, Iso5, in HNSCC." (PMID 36691359, 2023). "Additionally, POSTN plays a significant role in chemoresistance during cancer treatment." (PMID 35508298, 2022). "POSTN affects cancer cell proliferation via ERK and may promote EMT." (PMID 34281542, 2021). "Despite the report of the predicted molecular weight of POSTN, which is approximately 90 kDa, a molecular weight of approximately 40 kDa was confirmed by our Ex17 antibody from the bands observed from the supernatant or cell lysate fraction of fibroblasts or cancer cells." (PMID 33919736, 2021). "The differing roles of POSTN expression in stromal or cancer cells remain largely unknown." (PMID 33919736, 2021).
cancer (continued). "Finally, WNT signaling activation by CAF-secreted HGF in colorectal adenocarcinomas or by CAF-secreted POSTN in head and neck squamous cell carcinoma and BC cells may also promote cancer stemness and further metastatic initiation." (PMID 33553157, 2020). "However, periostin is also overexpressed in different cancers, including ovarian; reviewed in:." (PMID 31936272, 2020). "Interestingly the third most downregulated gene, POSTN (Periostin), is a multifunctional glycoprotein that plays a role in the adhesion process, in the migration of many cells, and importantly, in the epithelial-mesenchymal transition of cancer cells." (PMID 32511227, 2020). "In addition, POSTN is also expressed in inflammation and various cancers." (PMID 32271791, 2020). "POSTN is a vital downstream target in the transforming growth factor-β signaling pathway, which plays an essential role in the process of triggering and promoting the epithelial-mesenchymal transition, a key step in the induction of malignant characteristics in cancer cells." (PMID 31950035, 2019). "Thus, periostin-related pathways may play multiple roles in cancer malignancy and poor clinical outcomes." (PMID 30131847, 2018). "Importantly, when we analyzed 26 pairs of chemoresistant (cases with residual disease after neoadjuvant chemotherapy) human TNBC samples before and after chemotherapy, 19 cases showed significant upregulation of periostin at the cancer-stroma interface after chemotherapy." (PMID 29507310, 2018). "Notably, the deposition of Periostin from activated PSC selectively happens towards the invasive front of the cancer and this may influence the angiogenic activity." (PMID 27288147, 2016). "Additionally, animal studies support the pro-cancer properties of periostin in vivo." (PMID 26981774, 2016). "Moreover, POSTN was highly enriched in the stroma of cancer tissues and produced mainly by CAFs." (PMID 26857387, 2016). "Interestingly, we found an accumulation of periostin in both 67NR and 4T1 exosomes that could suggest a potential role of these exosomes in the maintenance of cancer stem cell properties." (PMID 27589561, 2016). "Changes in periostin expression are commonly detected in various cancers and pre-cancerous conditions, and periostin may be involved in regulating a diverse set of cancer cell activities that contribute to tumorigenesis, cancer progression, and metastasis." (PMID 25981515, 2015). "It is interesting to note that the ECM glycoproteins fibronectin, tenascin-C and periostin, that were found here among the most highly up-regulated genes during the angiogenic switch, have also been identified as crucial for metastatic colonization in other cancer models in vivo." (PMID 25301723, 2014). "However, little information is available on the expression of periostin protein in NSCLC cancer tissues, and the correlation between periostin expression and the clinicopathological characteristics of NSCLC patients is unknown." (PMID 24273600, 2013). "Periostin may be a suitable target to block the dangerous loop between cancer and inflammation." (PMID 24273600, 2013). "Finally, it was shown that periostin is expressed by stromal cells and by fibroblasts in cancer." (PMID 21489260, 2011). "However, the nature of periostin-producing cells in tumors is another matter of controversy as separate in situ hybridization experiments suggested that POSTN mRNA is detected in the cytoplasm of cancer cells." (PMID 18086302, 2007). "However, it is still unclear whether Periostin promotes invasion, angiogenesis and metastasis in actual cancer cases." (PMID 17060937, 2006).
cancer (continued). "However, it is still unclear whether Periostin is involved in invasion and metastasis in actual cancer cases." (PMID 17060937, 2006). "In this study, periostin expression was observed mainly in CAFs of 129 (36.8%) of all 351 CRC cases and on cancer cells in only 2 (0.6%) of the 351 CRC cases." (PMID 39941916, 2025). "Within the BCBM microenvironment, periostin (POSTN) is produced by POSTN-positive CAFs and promotes cancer cell proliferation by positively regulating the HGF-MET signaling pathway." (PMID 41219968, 2025). "As POSTN is a duplicated gene in zebrafish, we validated RNA probes for postna and postnb and analyzed both orthologues in the same zebrafish ONP cancer specimens used for IHC analyses." (PMID 39511408, 2025). "As CD26 expression can influence EMT induction in cancer, we analyzed the correlation of CD26 with the EMT phase markers E-cadherin, Vimentin, β-catenin, Elastin, Periostin, and Versican." (PMID 41426321, 2025). "Periostin contributes to airway remodeling and fibrosis in COPD and is overexpressed in several cancers, including NSCLC." (PMID 40826767, 2025). "Periostin expression was observed mainly in CAFs of 129 (36.8%) of all 351 CRC cases, and on cancer cells in only 2 (0.6%) of the 351 CRC cases." (PMID 39941916, 2025). "Periostin (POSTN) and podoplanin (PDPN) are both proteins playing an important role in humans in the diagnosis and study of many malignant tumours." (PMID 41361308, 2025). "Our in vitro studies confirmed expression of POSTN in three human MPNST cell lines, as well as expression of integrin receptors that mediate POSTN signaling in other human cancer types." (PMID 39511408, 2025). "It was related to enhanced expression of POSTN and the epithelial–mesenchymal transition (EMT) in cancer tissues." (PMID 39120301, 2024). "In the W2 cluster, DEGs include POSTN, MFAP4, DCN, and LUM, which are closely involved in extracellular matrix organization as well as in cancer invasiveness." (PMID 39190696, 2024). "Periostin modulates cancer cells proliferation, migration, and EMT, by its direct binding to integrins expressed on cancer cell surface." (PMID 38969910, 2024). "Secreted POSTN can promote cancer stemness in head and neck cancer, and RGN promotes dormancy in cancer cells." (PMID 38200509, 2024). "Likely, other factors co-act with TGFβ in the modulation of fibroblast phenotypic skew and microenvironment modulation in cancer, as also highlighted by the presence of other CAF-centric networks, including periostin and thombospondin." (PMID 39485038, 2024). "Additionally, periostin is hypothesized to play a pivotal role in cancer growth and progression." (PMID 39728072, 2024). "This suggests the possibility that another potential role of periostin in the TME is to support production of a lipid-based energy source and possibly to regulate lipid metabolism in cancer cells." (PMID 38049490, 2023). "To investigate the influence of extracellular periostin on apoptosis of cancer cells, we performed propidium iodide (PI) staining and a flow cytometry assay with HEYA8 cancer cells cultured with elevated periostin levels (CMPOSTNhigh)." (PMID 38049490, 2023). "The presence of periostin enhances cancer cell proliferation and the process of EMT cancers such as gastric cancer." (PMID 37092398, 2023). "Periostin, a stroma-specific molecule coded by the gene POSTN, was found to have a central role in the CTHRC1–PSC–cancer metastasis axis." (PMID 37444482, 2023). "Biomarkers (FAP, POSTN, PDGFRα/β, FSP-1, CD90, Palladin, OPN, AEBP1, TNC, CD10, and GPR77) represent cancer-promoting CAFs." (PMID 37476379, 2023). "Periostin, a stroma-specific molecule, demonstrated an essential role in the CTHRC1–PSCs–cancer metastasis axis." (PMID 37444482, 2023). "Many features of fibroblast activation are shared in other contexts, including cancer, where activated CAFs can strongly influence the TME and are the primary source of periostin." (PMID 35056404, 2022).